VIM (vimentin)
Diseases named in the same sentence as VIM in open-access papers (continued):
Sharing a sentence is not in itself a finding about the gene and the disease.
cancer (continued). "This study takes vimentin expression as an indicator for evaluating the anti-EMT potential of resveratrol, α-viniferin, ε-viniferin, and kobophenol A in TGF-β1- or IL-1β-induced A549, MCF-7, HOS, U2OS, NCI-H460 and NCI-H520 cancer cells using western blotting and immunofluorescence." (PMID 35684095, 2022). "In addition, we also analyzed the correlation between NUTF2 and the epithelial–mesenchymal transition (EMT) markers, Vimentin (VIM), TWIST1, Snail1 (SNAI1), Snail2 (SNAI2), Fibronectin 1 (FN1), and N‐cadherin (CDH2), which were widely accepted to be involved in cancer metastasis." (PMID 35155261, 2022). "Interestingly, expression of negative prognostic cancer markers, N-cadherin and vimentin, was strongly reduced in BBG-treated tumors." (PMID 34964926, 2022). "A lack of vimentin disables the cancer cells to promote actin polymerization." (PMID 36032170, 2022). "It displayed growth inhibitory effects on the cancer cells by reversing EMT‐induced changes in cell mobility and metastasis, and through further western blot analysis, it displayed an improvement in the E‐cadherin levels while the expression level of vimentin along with TGF‐β and Snail declined." (PMID 35384373, 2022). "In addition, although PKD1 can maintain an epithelial phenotype, via negatively regulating significant molecules that regulate EMTs in some cancer cells, this study demonstrates that PKD1 signaling in pNETs is required for concomitant expression of vimentin and E-cadherin in CSCs." (PMID 36497140, 2022). "Moreover, the anti-human-vimentin antibody utilized does not cross-react with mouse vimentin; thus, it is able to detect cancer cells even as single cells in mouse tissues." (PMID 35456719, 2022). "Another gene that plays an important role in EMT is Vimentin, a major component of the intermediate filament family of proteins, which is expressed in mesenchymal cells and is often used as a marker of EMT during both normal growth and metastatic progression of cancer." (PMID 35449812, 2022). "Moreover, pritumumab binds to the ecto-domain of vimentin on the surface of cancer cells with no off-target effects or not impairing the function of normal vimentin, thus offering an opportunity for testing in ARSACS models." (PMID 35892334, 2022). "Interestingly, treatment with vimentin promoted increased proliferation rates in the MCF-7 cancer cells but not in MCF-10a cells." (PMID 34299089, 2021). "Moreover, vimentin has been described as a negative prognostic marker in various cancers, and also in NSCLC, as extensively documented by numerous studies, then pooled in a meta-analysis." (PMID 34917615, 2021). "As a type III intermediate filament protein, vimentin contributes to subcellular and tissue‐specific biological functions and plays an important role in regulating EMT, which is widely thought to be an important mechanism contributing to the migration and metastasis of numerous cancer cells." (PMID 34605151, 2021). "It has been further hypothesized that cancer cells are significantly softer than their nontransformed counterparts, particularly in the context of stem-like states that express vimentin." (PMID 33691719, 2021). "Therefore, if we could find the molecule(s) to enhance the interaction between LINC01010 and vimentin, they might be drug candidates for treatment of HBV-related HCC or even other cancers." (PMID 34830378, 2021). "However, the functional role of extracellular vimentin in relation to cancer cells has not been studied." (PMID 34299089, 2021). "Vimentin filaments protect the cancer cells from mechanical stresses during the migration or squeezing through narrow spaces by providing a viscoelastic framework and support the positioning and integrity of organelles, especially the nucleus, during EMT and cancer progression." (PMID 34638469, 2021).
cancer (continued). "The data reported here show that surface vimentin enhances the invasive potential caused by the SARS-CoV-2 receptor binding domain (RBD) of the spike protein in monolayers of both non-tumorigenic (MCF-10a) and cancer (MCF-7) cells." (PMID 34299089, 2021). "The exact mechanism by which inversin could increase cancer invasion is at its infancy, however, modulating the epithelial–mesenchymal transition (EMT) by impairing E-cadherin expression and upregulating N-cadherin and Vimentin is a possible mechanism." (PMID 34947825, 2021). "Mesothelial cells are generally positive for calretinin, thrombomodulin, cytokeratin 5/6, WT1, D2-40, vimentin, HBME-1 and CD44H, while polyclonal and monoclonal carcinoembryonic antigen, Ber-EP4, Leu-M1, CA-125, B72.3, PAX8, MOC 31, CA19-9 and ER are the most common markers of carcinoma." (PMID 34068638, 2021). "Although the TEG derivatives decreased the expression of vimentin in cancer cells, they could not directly interact with the protein." (PMID 32751717, 2020). "In combination with FEC/TE, I2 treatment exhibited a synergic effect on cancer cell apoptosis and impaired expression of chemoresistance markers (BIRC5 and HIF1A) as well as changes in the expression of specific EMT markers (increased E-cad expression and decreased Vimentin expression)." (PMID 31319484, 2019). "In the later phases of cancer progression, TGF-β signaling can reduce expression of epithelial markers, such as E-cadherin, and promote epithelial-to-mesenchymal transition (EMT) by increasing the expression of mesenchymal markers including N-cadherin and vimentin." (PMID 31850854, 2019). "As the epithelial-to-mesenchymal transition (EMT) is a key driver of cancer metastasis, we determined the changes in several EMT-related proteins in NAP1 knockdown and control H661 cells, which showed dramatically reduced levels of Vimentin protein along with NAP1 depletion." (PMID 30867003, 2019). "However, the injected CAFs barely co-metastasized with carcinoma cells because of the absence of human-specific vimentin-positive stromal cells in the affected lungs." (PMID 31331982, 2019). "Finally, VIMENTIN, which also appeared dysregulated in the APC mut HIO (logCPM 9.32429, p-value 1.59E-30 and FDR 4.42E-28) is overexpressed in several cancers including gastrointestinal cancers and correlates with poor prognosis and accelerated growth and invasion of cancer cells." (PMID 30024920, 2018). "The initial results might indicate that the CD45neg/EpCAMneg nucleated cell population in the blood samples of cancer patients might contain cancer-related cells, particularly EMT transformed CTCs, as suggested by the high detection rate of vimentin gene expression." (PMID 30715062, 2018). "EOC is unique among cancers in that cancer cells have diverse progenitors, ovarian surface epithelium (OSE) and fimbrial epithelia, that express common epithelial markers as keratins, EpCAM and E-cadherin as well as mesenchymal markers as vimentin and N-cadherin." (PMID 29854318, 2018). "Moreover, DUSP2, p-ERK1/2 and EMT-related markers were examined in human PDAC tissues, which revealed that the miR-361-3p level in cancer tissues correlated negatively with the expression of DUSP2 and E-cadherin and positively with p-ERK, Vimentin and N-cadherin, respectively." (PMID 30042387, 2018). "A mesenchymal phenotype, characterised by low expression of E-cadherin (CDH1), high expression of vimentin (VIM) and high expression of EMT-inducing transcription factors, such as TWIST1, ZEB1, SNAI1 and SNAI2 moreover correlates with the expression of cancer stem cell markers CD44 and CD90." (PMID 29299154, 2017). "Immunostaining of CCR6, E-cadherin and Vimentin were calculated as DAB-positive signals per mm2 of total membrane surface area and cytoplasm of tissue sections, the expression of CCR6 was significantly higher in cancer tissues compared with adjacent normal tissue." (PMID 29383156, 2017).
cancer (continued). "Statistical analysis revealed the expression of vimentin in carcinoma and sarcomatoid cells was significantly different, which might be due to the lack of vimentin expression in 4 ChRCCs." (PMID 28449664, 2017). "Interestingly, vimentin and CTNNB1 over-expression and/or cytoplasmic accumulation (as we found in cancer cells expressing high level of MICAL2 in vitro) are both known predictors of hematogenous metastasis in human cancer." (PMID 26689989, 2016). "Furthermore, the incubation of TAMs conditioned medium resulted in a fibroblast-like appearance of cancer cells (HN4, HN6 and SCC9) together with the decreased/increased expression of E-cadherin/ vimentin, which were correlated with the enhanced ability of migration and invasion." (PMID 26769084, 2016). "Notably, vimentin staining of all the cancerous masses was negative indicating that cancer factors carried in the sera of all tested patients had integrated in the genome of the BRCA1-KO fibroblasts changing their fate permanently." (PMID 27179759, 2016). "We thus hypothesized that the mesenchymal status of cancer cells, exhibited through absence of E-cadherin expression and presence of vimentin expression, correlated with resistance to rapamycin both in vitro and in mouse xenografts." (PMID 25944619, 2015). "In addition, overexpression of vimentin in vimentin-negative MCF7 cells demonstrated the role of vimentin in cancer progression." (PMID 25965826, 2015). "In addition, there was marked elevation in expression levels of established biomarkers of EMT (i. e. zeb1; vimentin; snail; and slug) parallels similar cellular and molecular changes by which aberrant RANK signaling accelerates the progression of cancers to advanced stage disease." (PMID 26061636, 2015). "Vimentin expression was negative in N and H but positive in I. In the cancer samples, Vimentin expression was higher in A (SI: 2 to 6, median was 3.5) than in CIS (SI: 0 to 4, median was 2) (P = 0.017) and it was higher in AM (SI: 3 to 9, median was 6) than in A (P = 0.022)." (PMID 25189096, 2014). "However, the cancer cells in the MPP components expressed vimentin more extensively than those in the components without MPP." (PMID 25120667, 2014). "PSCs have also been shown to promote cancer cell migration, during which cancer cells exhibit features of epithelial-mesenchymal transition (EMT) namely, decreased levels of epithelial markers such as E-cadherin concurrent with increased expression of mesenchymal markers (vimentin and Snail)." (PMID 24592240, 2014). "Vimentin which was originally identified as an intermediate filament protein present only as an intracellular component has been detected recently on the surface of cancer cells but not on healthy cells in a punctate distribution pattern." (PMID 24502646, 2014). "Our study supports the hypothesis that FMCs are generally aggressive HRs negative cancers that manifest an heterogeneous phenotype characterized by basal cytokeratins and vimentin expression." (PMID 25249140, 2014). "In addition, to the best of our knowledge, the present study has provided the first evidence that cancer cells in the MPP component express vimentin more extensively than those in the non-MPP component in adenocarcinoma." (PMID 25120667, 2014). "Indeed, the number of vimentin-positive cells was dramatically different in infiltrating carcinomas with or without microcalcifications." (PMID 24758513, 2014). "Taken together, these results demonstrate that knockdown of plectin and vimentin decreases the motility of PC3 cell lines thus, supporting previous reports that down-regulation of these proteins is involved in invasion and migration important initial steps in cancer metastasis." (PMID 23717685, 2013).
cancer (continued). "Since vimentin is over expressed during EMT process, and NF-κB being one of the transcription factors binding to vimentin promoter, it would be tempting to speculate that this over-expression of vimentin is a result of activated NF-κB in cancer cells." (PMID 23785295, 2013). "However, rCCL5 did not induce epithelial-mesenchymal transition (EMT) as analyzed by Western blotting with anti-vimentin antibody, or proliferation of cancer cells (data not shown)." (PMID 24204919, 2013). "The HRG-β1-induced expressions of Snail, vimentin, and fibronectin, and nuclear colocalization of phospho-Smad2 and Snail were inhibited by pretreatment with a PI3k inhibitor, LY294002, or two phospho-Smad2 inhibitors, PD169316 or SB203580 and cancer cell migration by HRG-β1 was inhibited." (PMID 23937725, 2013). "In particular, γ-IR-treated cancer cells or mouse xenografts and metastatic lesions in mice bearing γ-IR-treated xenografts also display typical EMT marker expression patterns, such as increased vimentin or MMP-2 expression, decreased E-cadherin, and enhanced activity of MMP-2." (PMID 22963683, 2012). "In fact, test results for cytokines AE1 and AE2 were negative (excluding the diagnosis of carcinoma), vimentin and smooth muscle actin were positive (confirming the sarcomatous nature of the lesion), and the proliferation index ‘MIB1’ was quantified to 60 percent." (PMID 23176176, 2012). "For example, androgen withdrawal-induced marked downregulation of relaxin, VEGF, vimentin and BMP-6, involved in cancer progression as well as upregulation of cellular retinol binding protein 7 and interferon-γ receptor, negatively regulating cancer progression, in LNCaP/IL-6#1." (PMID 19844233, 2009). "Furthermore, vimentin staining of the tumors that never reached the doubling endpoint in the combination group revealed the presence of remaining cancer cells, indicating that longer treatments times would be required to potentially eradicate orthotopic MDA-MB-231 tumors in mice." (PMID 39730333, 2024). "Moreover, EMT can transform vimentin-positive non-CSCs into cancer stem cells." (PMID 38383479, 2024). "While prior studies established a role for vimentin in cancer cells, these experiments relied on either cell lines treated with exogenous agents to suppress vimentin expression or cells derived from the vimentin knockout (Vim−/−) mice that lacked oncogene activation." (PMID 37161053, 2023). "Besides individual CRCs, CTM which displayed CD45-/PD-L1+/CD31-/Vimentin- phenotypes was also detected in diagnosed cancer patients’ peripheral blood, and for the non-neoplastic infectious patients, we could only observe CTM with no biomarker expression." (PMID 35311070, 2022). "In conclusion, our results demonstrate that vimentin promotes the biogenesis and the release of cancer exosomes, and that a reversible vimentin-binding compound can block cancer exosome release and inhibit cancer cell migration and invasion without cytotoxic effects." (PMID 34305581, 2021). "In addition, the expression of Slug and Vimentin, the markers of epithelial-to-mesenchymal transition (EMT) involved in cancer metastasis, was downregulated by miR-489 overexpression or SIX1 knockdown, suggesting that the miR-489/SIX1 axis may play a role in metastasis." (PMID 32258386, 2020). "This is the first report that ajoene directly targets and covalently modifies vimentin in cancer cells and it is therefore not known whether vimentin targeting also occurs for other garlic organosulfur compounds; and conversely whether inhibition of other EMT processes may also occur for ajoene." (PMID 30894168, 2019). "Furthermore, STYK1’s mechanism of promoting cancer cell mobility and epithelial-mesenchymal transition (EMT) was found to be via the MEK/ERK and PI3K/AKT pathways, resulting in increased expression of mesenchymal protein markers: snail, fibronectin, and vimentin, and decreased E-cadherin expression." (PMID 27628214, 2016).
cancer (continued). "In this current study, several CAFGs—VIM, ANXA1, HOPX, CALD1, and COL8A1—were confirmed highly expressed in TC cells, but not in those of other cancers (except ANXA1 in PDAC)." (PMID 41228323, 2025). "BAPTA-AM pre-treatment of LAD2 cells did not affect Vimentin levels in LAD2 cells, further confirming the absence of contamination from the LAD2 cell fraction to the cancer cell fraction." (PMID 41039118, 2025). "On the contrary, other genes, such as VIM and MMP9, seemed completely nonspecific and not correlated to an increase in cancer cell aggressiveness." (PMID 40332096, 2025). "In cancer cell lines, overexpression of wild‐type (WT) PRMT1, but not catalytically inactive mutants (E133Q and E142Q), enhanced vimentin R64 aDMA in both HeLa and A549 cells stably expressing Flag‐vimentin." (PMID 40884268, 2025). "Of note, carcinoma areas expressing E-CAD/pAMPK, lacking VIM/GLUT1, were observed in macro-metastases, indicative of luminal differentiation driving MET (part of area 5)." (PMID 38238426, 2024). "CAFs were positive for vimentin (VIM) and alpha-smooth muscle actin (ASMA), but negative for cytokeratin (CK) expression ensuring that CAFs culture is not contaminated by cancer cells." (PMID 37480115, 2023). "Results indicated that using both EpCAM and vimentin antibodies significantly improved CTC isolation compared to using either marker alone, regardless of cancer stage." (PMID 37345161, 2023). "While changes in expression of TGF-β, ZEB1, SNAI1, MMPs, vimentin, and E-cadherin are hallmarks of an EMT process occurring within cancer cells, including cSCC cells, EMT within tissues is not an “all or none” process." (PMID 36012449, 2022). "Both noninvasive and invasive cancer cells can express the EMT markers β-catenin and vimentin or S100A4, so these are also not unique to CAFs." (PMID 36010899, 2022). "In this study, we investigated the functional role of extracellular vimentin in non-tumorigenic (MCF-10a) and cancer (MCF-7) cells through the evaluation of its effects on cell migration, proliferation, adhesion, and monolayer permeability." (PMID 34299089, 2021). "The results of ICC staining showed that the expression of E-cadherin was decreased, while that of vimentin, Snail, and Twist was markedly increased in LoVo and Hct116 cells after treatment with ATO compared to control cancer cells without ATO treatment." (PMID 34676163, 2021). "Immunohistochemical studies showed that the carcinoma cells were positive for pancytokeratin AE1/AE3 and low molecular weight cytokeratin CK8/18, and negative for the mesenchymal marker vimentin." (PMID 33761637, 2021). "We found that E-cadherin was transcriptionally downregulated, whereas mRNA of N-cadherin and vimentin was increased in Ctsl−/− cells, with no changes in fibronectin, supporting the previous observation of de-differentiation in MMTV-Cre/Ctsl−/− cancers." (PMID 32707827, 2020). "We observed that CCRCC shows mesenchymal characteristics with high VIM and low CDH1 expression unlike other cancer types which reflects epithelial characteristics with high CDH1 and low VIM expressions." (PMID 32033228, 2020). "Unlike these cancer cell lines, the inhibition of PD-L1 in MDA-MB-231 did not affect the snail/vimentin-induced EMT pathway." (PMID 31349612, 2019). "We found that phosphorylation of STAT3 Y705 but not S727 promoted cancer cell EMT and metastasis through the Slug-mediated regulation of E-cadherin and Vimentin." (PMID 31597912, 2019). "TE9 cancer cells pre-treated with VPA exhibited less inhibition of E-cadherin expression and no increase of vimentin expression as compared with untreated cells stimulated by TGF-β1 or irradiation." (PMID 30691229, 2019). "IHC staining was used to evaluate the expression of E-cadherin (epithelial marker) and vimentin (mesenchymal marker) in Kazakh ESCC and cancer-adjacent normal tissues (CANs)." (PMID 31186031, 2019).